MAT1A (methionine adenosyltransferase 1A)
Diseases named in the same sentence as MAT1A in open-access papers (continued):
Sharing a sentence is not in itself a finding about the gene and the disease.
hypermethioninemia (10 papers, 2015 to 2024). "The long-term prognosis of patients with simple hypermethioninemia due to MAT1A gene mutations, particularly damage to the central nervous system, remains challenging." (PMID 39705457, 2024). "Ultimately, genetic testing confirmed hypermethioninemia, which was attributed to a mutation in the MAT1A gene." (PMID 39705457, 2024). "We translated the clinical data of 10 patients with hypermethioninemia due to MAT1A gene mutation from our center, which provides a basis for clinical diagnosis, genetic counseling, and follow-up management." (PMID 39705457, 2024). "Hypermethioninemia due to MAT1A mutation was diagnosed in a child (Patient 156) with DD, who was subsequently treated with a methionine-restricted diet in combination with rehabilitation treatment after diagnosis and experienced significant growth improvement." (PMID 38649797, 2024). "The objective of this study is to provide a foundation for clinical diagnosis, genetic counseling, and follow-up management of hypermethioninemia caused by MAT1A gene defects." (PMID 39705457, 2024). "The high clinical heterogeneity of hypermethioninemia caused by MAT1A gene defects has resulted in a paucity of studies examining the association between clinical phenotypes, biochemical characteristics, and gene mutations in this patient group." (PMID 39705457, 2024). "In 13 patients with hypermethioninemia, five mutations were detected and the c.791G > A was the most common mutation in MAT1A gene, accounting for 71.4% of mutational alleles and 76.9% of patients." (PMID 31737040, 2019). "A common cause of elevated methionine in newborn screening is the autosomal dominant form of hypermethioninemia due to monoallelic mutations of MAT1A." (PMID 27671891, 2017). "The majority of newborns now being flagged for methionine elevations in screening programs with lowered methionine cut-off values are turning out to be heterozygotes for one of the MAT1A mutations now known to cause mild to moderate hypermethioninemia." (PMID 26289392, 2015). "As screening of newborns for methionine elevations has expanded, MAT1A mutations are turning out to be the most common genetic cause of newborn hypermethioninemia." (PMID 26289392, 2015). "Hypermethioninemia is caused by the deficiency of glycine N-methyltransferase (GNMT) activity and/or mutations of the MAT1A gene, which resulted in the plasma concentration of methionine reaching as high as 1870 μM (normal range 5–35 μM)." (PMID 32528425, 2020). "Hypermethioninemia is able to be inherited by dominant transmission of MAT1A (MIM* 610550) gene." (PMID 31737040, 2019). "However, although hepatic MAT1A and MAT2A expression is up-regulated at the protein level after MAT2A inhibition, the capacity of the liver of treated animals to metabolize methionine is markedly diminished, which leads to hypermethioninemia and subsequent reduced SAM levels." (PMID 38755480, 2024).
Hepatic steatosis (5 papers, 2022 to 2024). Steatosis is a term used to denote lipid accumulation within hepatocytes. "Reduced Mat1a function is strongly associated with metabolic disorders, in particular fatty liver disease characterized by lipid accumulation and immune dysfunction, which rendered Mat1a-/- mice more susceptible to liver injury." (PMID 37772039, 2023). "Worsened hepatic steatosis was also associated with increased hepatic very low-density lipoprotein (VLDL) -TG secretion in MAT1A deficient mice." (PMID 36171419, 2022). "Some studies show that SAMe deficiency promoted the development of NAFLD in MAT1A knocked-out mice, and supplementation with betaine and taurine to high-fat-diet-induced obese mice improved hepatic steatosis and restored insulin sensitivity." (PMID 35893906, 2022). "It should be noted that MAT1A deficiency has been linked to increased liver steatosis and injury via other mechanisms in addition to reduced liver CoA." (PMID 36171419, 2022). "Taken together, these results suggest that MAT1A deficiency contributes to hepatic cysteine and CoA deficiency and susceptibility to hepatic steatosis, and selective hepatic cysteine enrichment and stimulation of CoA synthesis are largely mediated by TFEB induction of hepatic MAT1A." (PMID 36171419, 2022). "After MAT1A knockout mice develop spontaneous hepatic steatosis at an older age, their hepatic VLDL-TG significantly increases, which resembles our findings in liver MAT1A knockdown mice with worsened hepatic steatosis." (PMID 36171419, 2022). "In addition, MAT1A KO mice are more likely to develop fatty liver disease when fed a choline-depleted diet." (PMID 38755480, 2024). "Of note, 3 months old MAT1A KO mice did not exhibit altered hepatic lipid content or major liver damage, although at this age they were more susceptible to choline-deficient diet-induced fatty liver." (PMID 38755480, 2024). "However, there is no histopathological evidence of liver steatosis in MAT2Ai-treated mice, which contrasts with observations in MAT1A KO mice." (PMID 38755480, 2024). "The magnitude of TFEB-mediated hepatic TG reduction was attenuated but not fully abolished upon MAT1A knockdown, which is expected since TFEB is known to lower hepatic steatosis via other mechanisms." (PMID 36171419, 2022).
liver cirrhosis (5 papers, 2008 to 2022). "SAM is synthesized from methionine by the enzyme methionine adenosyltransferase, which is encoded by the genes MAT1A and MAT2A (Mat1a and Mat2a in mice); patients with liver cirrhosis have a 50%-reduced activity of this enzyme." (PMID 29285212, 2017). "Indeed, patients with liver cirrhosis show low Mat1a levels and lower production of SAMe41." (PMID 35232994, 2022). "Liver cirrhosis and HCC of rodents and humans are characterized by a decrease of MAT1A expression and a rise in MAT2A expression with a consequent decrease of MAT1A:MAT2A ratio (the so-called MAT1A/MAT2A switch)." (PMID 35159219, 2022).
alcoholic hepatitis (4 papers, 2019 to 2024). Acute hepatitis resulting from ingestion of alcohol. "Liver samples from normal and alcoholic hepatitis (AH) patients revealed a 40% reduction in total MATα1 protein levels and a 70% reduction in MAT1A mRNA levels, the latter being consistent with the GSE28619 database." (PMID 35091576, 2022). "Since SAM is the principal donor of the methyl group in multiple physiological processes, MAT1A and MAT2A may participate in various inflammatory diseases, such as experimental autoimmune encephalomyelitis, alcoholic hepatitis, non-alcoholic fatty liver diseases, and inflammatory bowel diseases." (PMID 38130504, 2024).
Obesity (4 papers, 2022 to 2025). Accumulation of substantial excess body fat. "The results showed that targeting Mat1a prevents and reverses obesity as well as obesity-associated dyslipidemia, insulin resistance and hepatosteatosis." (PMID 35232994, 2022). "We demonstrate that ASO-mediated silencing of Mat1a reverses and prevents obesity, insulin resistance and the associated hepatosteatosis as well as reducing lipids in serum." (PMID 35232994, 2022). "In the context of obesity, the beneficial effects driven by Mat1a deficiency closely resembles those produced by dietary MR." (PMID 35232994, 2022). "Thus, in this context of obesity, the results suggest that deficiency of Mat1a induces the secretion of FGF21 through activation of NRF2." (PMID 35232994, 2022). "Therefore, we investigated if targeting Mat1a could improve and/or prevent obesity and the associated whole-body metabolic dysregulation." (PMID 35232994, 2022). "Our results here confirm that targeting Mat1a protects the liver from the obesity-induced hepatosteatosis through the formation of FGF21." (PMID 35232994, 2022). "In conclusion, targeting Mat1a prevents and reverses obesity and the obesity-related insulin resistance and hepatosteatosis." (PMID 35232994, 2022). "Here, we investigated if the pharmacological (antisense oligonucleotide (ASO) treatment) knockdown of the Mat1a gene, which is involved in the first reaction of the methionine cycle, provides beneficial outcomes in diet- and genetically- induced obesity and obesity-related NAFLD." (PMID 35232994, 2022). "Thus, the results here demonstrated that targeting Mat1a improves the obesity-related hepatosteatosis." (PMID 35232994, 2022). "Finally, we propose that silencing Mat1a in obesity activates NRF2 in hepatocytes and induces the secretion of FGF21 to the general circulation, which increases WAT lipolysis and BAT thermogenesis, decreasing de novo lipogenesis in the liver." (PMID 35232994, 2022). "Interestingly, in the context of obesity, we show here that Mat1a deficiency, rather than worsening the liver status, decreased the de novo lipogenesis in the liver, without affecting FAO, preventing lipid accumulation without producing liver fibrosis or infiltration." (PMID 35232994, 2022). "Our results demonstrate that targeting Mat1a promotes the secretion of FGF21 in both, DIO and genetically induced obesity (ob/ob mice) models." (PMID 35232994, 2022). "Mat1a ASO prevents and reverses obesity by inducing BAT thermogenesis." (PMID 35232994, 2022). "Thus, targeting Mat1a activates the liver-BAT axis by increasing NRF2-mediated FGF21 secretion, which prevents obesity, insulin resistance and hepatosteatosis." (PMID 35232994, 2022).
alcoholic fatty liver disease (3 papers, 2023 to 2025). Lipid infiltration of the hepatic parenchymal cells that is due to alcohol abuse. "This is reminiscent of mammalian studies showing loss of MAT1A in mammalian liver impacts mitochondria and may underlie changes occurring in alcoholic fatty liver disease." (PMID 40027629, 2025). "Downregulation of MAT1A, with consequent reduced synthesis of SAM from methionine, and lower rates of methionine transmethylation are often present in non-alcoholic fatty liver disease patients." (PMID 36322288, 2023).
bladder cancer (3 papers, 2019 to 2023). "MAT1A, which can enhance cell survival under chemotherapy, has been associated with drug resistance in bladder cancer PDX mice." (PMID 33282950, 2020). "Methyltransferases of various types have been previously implicated in cancer progression, however for the first time, we showed that MAT1A elevated levels confer a significant survival advantage in bladder cancer cells during drug exposure." (PMID 31600961, 2019). "As such, MAT1A RNA expression is not endogenous to any of the cells residing in the healthy urinary bladder, and MAT1A transcription initiates in bladder cancer cells after the epithelia undergo oncogenic transformation." (PMID 31600961, 2019). "MAT1A expression was next quantified in vitro, in 5637 human bladder cancer cells throughout a 48 h exposure to gemcitabine as well as during a 12 day post treatment recovery period." (PMID 31600961, 2019). "To determine whether MAT1A expression found in PDX models of bladder cancer relapse is also broadly observed in tumors harvested from patients that received chemotherapy, we examined MAT1A protein expression by IHC in bladder cancer biopsies from 55 patients." (PMID 31600961, 2019). "Overexpression of MAT1A in 5637 bladder cancer cells increased tolerance to gemcitabine and stalled cell proliferation rates, suggesting MAT1A upregulation as a potential mechanism by which bladder cancer cells persist in a quiescent state to evade chemotherapy." (PMID 31600961, 2019). "Interestingly, MAT1A is not expressed in the urinary bladder under normal conditions, further suggesting the importance of this work as a novel biomarker for bladder cancer." (PMID 31600961, 2019).
breast carcinoma (3 papers, 2021 to 2024). "Kamalesh Dattaram Mumbrekar describes the sensitivity of mutations in the CD44 and MAT1A genes to acute skin reactions in breast cancer patients undergoing radiotherapy." (PMID 38380359, 2024). "Index patient 2 presented three likely pathogenic variants SLC3A1 c.1400T > C, MAT1A c.826dupG, and PTGIS c.824G > A. Breast cancer cells have elevated expression of SLC3A1, which accelerates cysteine uptake and accumulates reduced glutathione and decreases reactive oxygen species in tumor cells." (PMID 37628631, 2023). "The GNMT and MAT1A protein expressions and the C/N ratio of MAT2A were also correlated with the five-year relative survival rate in our breast cancer cohort." (PMID 34065390, 2021). "GNMT, MAT1A, MAT2A-biomarker IHC panel was compared with the clinical survival record in breast cancer patients, to examine the accuracy of IHC-based methods for identifying clinical prognosis." (PMID 34065390, 2021). "mRNA expression of GNMT and MAT1A was not related to breast cancer survival." (PMID 34065390, 2021).
dyslipidemia (3 papers, 2021 to 2022). "In support of the functional relevance of SAM/MAT1A in metabolic disease, MAT1A-knockout mice show NASH and dyslipidemia." (PMID 36260611, 2022).
liver fibrosis (3 papers, 2022 to 2024). "Reduced MAT1A and PEMT expression were also observed in patients with NASH and liver fibrosis." (PMID 39795274, 2024). "Furthermore, although dispersion of the data was high, the Sirius Red and F4/80 immunostaining and the expression levels of genes involved in fibrosis and inflammation, showed that treatment with Mat1a ASO did not induce the increase of liver fibrosis or inflammation." (PMID 35232994, 2022).
cholangiocarcinoma (2 papers, 2025 to 2026). A carcinoma that arises from the intrahepatic biliary tree (intrahepatic cholangiocarcinoma) or from the junction, or adjacent to the junction, of the right and left hepatic ducts (hilar cholangiocarcinoma). "Among them, c-Myc binds to E-box elements, increasing promoter activities such as that of MAT1A when associated with MafG and c-Maf, a complex that can also include MATα1 in cases of cholestatic livers and cholangiocarcinoma." (PMID 40141131, 2025). "High methylation of the MAT1A promoter has been observed in cholangiocarcinoma." (PMID 41513616, 2026).
Hepatitis (2 papers, 2019 to 2021). Inflammation of the liver. "Patients with liver injury, such as fibrosis and hepatitis, have decreased expression of MAT1A and hepatic SAM levels, which contributes to diminished hepatic glutathione (GSH) levels in these cases." (PMID 33753727, 2021).
hyperhomocysteinemia (2 papers, 2024 to 2025). A serious metabolic condition caused by mutations in the MTHFR gene, medications, or nutritional deficiency. "Hyperhomocysteinemia caused by mutations in the MAT1A gene can be diagnosed by combining relevant biochemical indices with the results of genetic testing." (PMID 39705457, 2024).
Hypertension (2 papers, 2012 to 2022). The presence of chronic increased pressure in the systemic arterial system. "MAT1A variants have been shown to be associated with hypertension and stroke." (PMID 22496743, 2012). "The Met adenosyltransferase (MAT) 1a (MAT1A) gene, which encodes the major hepatic forms of the MAT protein, MATI and III, has been found to be strongly associated with hypertension." (PMID 36352848, 2022).
radiation dermatitis (2 papers, 2024 to 2025). "Genotyping of single nucleotide polymorphisms (GSTA1 rs3957356-CT, MAT1A rs2282367-GG) may be linked to the degree of pruritus in radiation dermatitis." (PMID 38814489, 2024). "The reason may be that symptoms of radiodermatitis itchiness are associated with serine proteases (e.g. KLK, matriptase, prostaglandins, or trypsin-like enzymes) and single nucleotide polymorphism genotyping (GSTA1 rs3957356-CT, MAT1A rs2282367-GG)." (PMID 40768536, 2025).
Wilson disease (2 papers, 2016 to 2017). A very rare inherited multisystemic disease presenting non-specific neurological, hepatic, psychiatric or osseo-muscular manifestations due to excessive copper deposition in the body. "The decrease in MAT1A expression is in agreement with the results found in LEC rats as well as in cirrhotic livers of Wilson disease patients." (PMID 28459846, 2017). "Livers of 9-week old LEC rats, a model of Wilson disease, exhibited a moderate decrease in Mat1a expression (~20%) that was not followed by changes in Pdrg1 expression as compared to the controls." (PMID 27548429, 2016).
Anxiety (1 paper, 2022). Intense feelings of nervousness, tension, or panic often arise in response to interpersonal stresses. "The liver‐specific suppression of Mat1a in naïve animals attenuated circulating and central SAM levels as well as brain RNA methylation, leading to depressed cortical activity and anxiety‐like behaviors." (PMID 35642952, 2022).
bladder tumors (1 paper, 2019). "Evidence of MAT1A in bladder tumors may prove as a powerful prognostic tool to evaluate surgical margins and indicate likelihood of relapse in histopathology samples." (PMID 31600961, 2019).
breast tumor (1 paper, 2021). "Conversely, the increased MAT1A in the breast tumor compared to the control tissues implied a potential role of oncogene that may deserve attention in future studies." (PMID 34065390, 2021). "We examined the specimens from 252 independent patients and compared the subcellular protein expression of GNMT, MAT1A, and MAT2A between the breast tumor and their paired normal breast tissues by Immunohistochemistry (IHC) analysis." (PMID 34065390, 2021).
demyelination (1 paper, 2019). "There is a wide range of clinical manifestations in individuals with mutations in MAT1A gene, from completely asymptomatic to neurological problems associated with brain demyelination." (PMID 31737040, 2019).
fibrosis (1 paper, 2022). the formation of excess fibrous connective tissue in an organ or tissue in a reparative or reactive process. "Our previously published microarray analysis of humans with NAFLD showed that MAT1A expression is suppressed in livers with advanced vs mild NAFLD fibrosis." (PMID 36535507, 2022).
Glucose intolerance (1 paper, 2022). Glucose intolerance (GI) can be defined as dysglycemia that comprises both prediabetes and diabetes. "Similarly, as occurred with mice treated with Mat1a ASOs, food intake maintained unaltered whereas the GTT and ITT showed that Mat1a-KO mice were protected from the HFD-induced glucose intolerance and insulin resistance." (PMID 35232994, 2022).
keloid (1 paper, 2025). An irregularly shaped, elevated mark on the skin caused by deposits of excessive amounts of collagen during wound healing. "Heat maps showed decreased expression of genes involved in Hcy catabolism, including CBS, MTR, 5-methylenetetrahydrofolate homocysteine methyltransferase reductase (MTRR), methylenetetrahydrofolate reductase (MTHFR), and methionine adenosyltransferase 1a (MAT1A) in keloids." (PMID 39919369, 2025).
methionine adenosyltransferase deficiency (1 paper, 2022). "Methionine adenosyltransferase deficiency (MATD) is a rare metabolic disorder caused by mono- or biallelic MAT1A mutations that are not yet well understood." (PMID 36704196, 2022).
necrotizing enterocolitis (1 paper, 2025). Necrotizing enterocolitis (NEC) is a devastating disease that affects mostly the intestine of premature infants. "The findings of this study unravel a previously unrecognized regulatory axis involving AHSG, BHMT2, and MAT1A that orchestrates macrophage polarization and contributes to the exacerbation of necrotizing enterocolitis." (PMID 41219226, 2025).
sarcoidosis (1 paper, 2025). Sarcoidosis is a multisystemic disorder of unknown cause characterized by the formation of immune granulomas in involved organs. "Finally, no clear evidence linking ACOXL, MAT1A, or MACROD1 to sarcoidosis or immune (dys)regulation was found from the available literature." (PMID 41466414, 2025). "Finally, at least 8 additional genes have been implicated in immune regulatory response, whereas no clear evidence linking ACOXL, MAT1A, or MACROD1 to sarcoidosis or immune (dys)regulation was found from the available literature." (PMID 41466414, 2025).